EGFR (epidermal growth factor receptor)
Diseases named in the same sentence as EGFR in open-access papers (continued):
Sharing a sentence is not in itself a finding about the gene and the disease.
cancer (continued). "In the setting of environmental exposures to toxic agents that are able to induce DNA damage such as heat, radiation, hydrogen peroxide, and chemotherapeutic agents most notably cisplatin, cancer cells are able to activate a nuclear EGFR pathway in which promotes DNA repair and cell survival." (PMID 23119048, 2012). "Moreover, recent studies have revealed a critical role of STAT3 in maintaining EGFR-mediated cancer cell proliferation." (PMID 23118721, 2012). "From a chemopreventive perspective EGFR may be an important target as revealed by the mechanistic evaluation of green tea extract for cancer chemoprevention." (PMID 22675506, 2012). "Interestingly, the anticancer drug, curcumin, down-regulates AQP3 expression in cancer ovarian cells via a mechanism that involves, at least partially, inhibition of the EGFR pathway and downstream AKT." (PMID 23017148, 2012). "According to studies on epitope structure of tumor-associated epidermal growth factor receptor (EGFR), EGFR overexpression on cancer cells exposes neo-epitope that is not found in EGFR on normal tissues." (PMID 22989299, 2012). "Curcumin used as a single agent or in combination with other chemotherapeutics might offer more clinical benefits through promoting EGFR degradation, manipulating miRNA expression profiles, triggering cancer cell autophagy and eliminating CSC, respectively." (PMID 22489192, 2012). "In many human cancers, EGFR plays a central role in promoting cell proliferation." (PMID 23119029, 2012). "As such, antagonists of EGFR or integrin αvβ5 may provide new therapeutic options to target malignant tumors expressing MUC1." (PMID 22586492, 2012). "Finally, exposure to agents targeting EGFR in vitro and in vivo alters the profiles of cancer cell-derived EVs." (PMID 26082068, 2012). "Also, improved screening methods for EGFR and other cancer-specific abnormalities, should be incorporated into routine clinical diagnostic testing to pave the way for early diagnosis and improved survival in OSCC." (PMID 22359620, 2012). "In its behavior as an oncogene, EGFR can promote acquisition of cancer stem cell-like properties in HNSCC cancer cells and may determine the fate of progenitor cells, thus making it an attractive therapeutic target." (PMID 22384257, 2012). "Some studies indicate the role of STAT3 in EGFR signaling in various cancers." (PMID 22824293, 2012). "Erlotinib, another EGFR-TKI anti-cancer drug, produced similar inhibitory effects to gefitinib." (PMID 22957020, 2012). "The epidermal growth factor receptor (EGFR) is a well-established target for cancer treatment." (PMID 22957020, 2012). "Thus, EGFR and its downstream signals were clearly up-regulated in the ES-2 cancer cell-induced peritoneal metastasis models both in vitro and in vivo." (PMID 23046546, 2012). "The EGFR protein is an important therapeutic target for cancer." (PMID 22554165, 2012). "EGFR is involved in various steps of cancer development including tumorigenesis, invasion, metastasis, and angiogenesis, and thus provides an attractive target for cancer drug development." (PMID 22957020, 2012). "Cetuximab is a monoclonal antibody that targets overexpressed EGFR in various cancers." (PMID 22619725, 2012). "Our findings suggest that in cases of NSCLC accompanied by mutant EGFR, treatment targeting inhibition of EGFR kinase activity in differentiated cancer cells may generate a population of cancer cells with stem cell properties." (PMID 22433462, 2012). "Indeed, one of the most studied intracellular cross-talk mechanisms that occur in cancer is the link between the epidermal growth factor receptor (erbB/HER) family and the insulin-like growth factor receptor (IGFR)." (PMID 23202921, 2012).
cancer (continued). "Amongst the best described examples of oncoproteins found in the cargo of cancer-derived oncosomes are members of the ErbB/HER family of receptor tyrosine kinases (RTKs), such as activated (phosphorylated) EGFR and its constitutively active mutant EGFR variant III (EGFRvIII)." (PMID 22934045, 2012). "Over expressed levels of the EGFR have been reported in neck and head, colon, lung, breast, stomach, bladder, oesophagus, cervix, ovary and endometrium cancers which repeatedly appear to denote cancer prediction." (PMID 23133538, 2012). "In addition, we have found that EGFR promotes invasion and chemoresistance in a putative cancer stem cell culture, suggesting that EGFR also regulates malignant behavior in cancer stem cells." (PMID 22384257, 2012). "In addition, we found that the rates of mPRα-HiEx were significantly higher in cancers with epithelial growth factor receptor–1 (EGFR+) and high level of Ki67 expression, indicating positive correlation between mPRα over expression and EGFR or Ki67." (PMID 22496908, 2012). "Historically, however, the EGFR has been more commonly associated with cancer biology as opposed to neuronal function, metabolism, or aging." (PMID 22754566, 2012). "Indeed, a previous study has revealed a role of cancer cell-expressed ADAMTS1 in metastasis with a mechanism involving activation of epidermal growth factor receptor and ErbB-2 and shedding of amphiregulin and heparin-bound epidermal growth factor precursors." (PMID 22514714, 2012). "Therefore, a complete understanding of how the EGFR functions has important implications in developmental biology, tissue repair, and cancer biology." (PMID 23344022, 2012). "We first sought to determine whether EGFR might regulate the expression of a set of well-established cancer stem cell markers." (PMID 22384257, 2012). "Our findings may have implications for the use and future design of targeted therapies in cancers known to express EGFR, Src, or MUC1." (PMID 22586492, 2012). "Treatment of HNSCC cells and xenografts with the combination of antibodies to IGF-1R and EGFR was more effective than either agent alone at reducing cancer cell growth, suggesting a potential benefit in the use of combined anti-tyrosine kinase receptor directed therapies to treat HNSCC." (PMID 22545054, 2012). "However, the EGFR is also important in normal skin development and disproportionately affected when inhibitors of the receptor are administered in cancer therapy." (PMID 25031940, 2012). "Here, we hypothesized that aberrant activation of EGFR is one of the key steps that has resulted in the pathogenesis of HNSCC cancer stem cells." (PMID 22384257, 2012). "Therefore, in the presence of a dominant growth pathway, cancer cells are capable of responding to other growth factors, compromising the antitumor activity of agents designed specifically to inhibit EGFR." (PMID 22545054, 2012). "This suggests that EGFR overexpression is an important event in cancer development and progression." (PMID 23233863, 2012). "In addition, clinical findings showed an inverse correlation between ERβ1 positivity and expression of EGFR, a crucial component in basal-like cancers that drives proliferation and EMT." (PMID 23158001, 2012). "The activation of EGFR pathways has been shown to be involved in tumorigenesis in many cancers." (PMID 23046546, 2012). "EGFR is overly expressed in many cancers, including 40–80% of NSCLC." (PMID 23119048, 2012).
cancer (continued). "The epidermal growth factor receptor (EGFR) signaling pathway is one of the best investigated cellular signaling pathways regulating important cellular processes and its deregulation is associated with severe diseases, such as cancer." (PMID 22253908, 2012). "Our and others' results suggest that the presence of a KRAS mutation (or other unknown alterations in these cells) could render H358 cells dependent on EGFR signaling and that EGFR would be a candidate therapeutic target in such cancers." (PMID 22436374, 2012). "Inhibition of EGFR activation has been shown to suppress the growth of human cancer cells." (PMID 22952709, 2012). "Increased mRNA expression of EGFR was observed in both cell lines overexpressing TFPIα or TFPIβ, and it was identified as a key molecule in the functional and network analyses, in connection to both Cancer and Inflammation." (PMID 23071754, 2012). "Given that CD44 is the main stem cell marker for HNSCC, these results suggest that EGFR activation may be crucial for maintaining a cancer stem cell phenotype." (PMID 22384257, 2012). "However, constitutive activating mutations in signaling components downstream of EGFR, like NRAS(Q61L) or BRAF(V600E), are common in cancer cells." (PMID 22253908, 2012). "GPER may thus play a role in cancer cell proliferation possibly through trans-activation of EGFR, or as an ERα collaborator." (PMID 22424333, 2012). "PI3 K-PDK-AKT-mTOR is a downstream target of EGFR, activated in cancer." (PMID 23209942, 2012). "Our results suggest EGFR inhibition might be an effective method to target the cancer stem cell population in HNSCC." (PMID 22384257, 2012). "In fact, shedding of EGFR and other oncoproteins as EV cargo may represent a mechanism of removal of these overabundant molecules from their parental cancer cells, and could be reiterated in EV recipients." (PMID 22934045, 2012). "Changes that slow the progression of the EGFR through the endocytic pathway, enhance signaling, and can lead to increased cell proliferation, differentiation, migration, as well as other hallmarks of cancer." (PMID 23344022, 2012). "In addition, EGFR is involved in the pathogenesis and maintenance of several human cancers of epithelial origin." (PMID 23233863, 2012). "Remarkably, combined treatment with cetuximab and the aptamer shows clear synergy in inducing apoptosis and inhibiting tumor growth in a mouse xenograft model of human cancer, thus resulting in the first report of an anti-EGFR aptamer whose activity has been proved in vivo." (PMID 22685651, 2012). "Although it is known that EGFR facilitates cancer progression by inducing cell growth and proliferation, these effects alone may not be enough to overcome the natural barriers of senescence and terminal differentiation." (PMID 22384257, 2012). "Accelerating EGFR trafficking is predicted to decrease the growth factor-dependent survival of a cancer cell, but could disrupt epithelial cells homeostasis in other tissues." (PMID 23344022, 2012). "Cancer cells organize the energy requirement by reorienting lipogenic/lipolytic metabolic balance to provide for and sustain the cancer growth by redefining functions of EGFR, PPAR-gamma, and fatty acid synthesis and glycolysis machinery." (PMID 22509304, 2012). "Detecting expression levels of EGFR profile in vivo could be helpful for detecting and characterizing malignant tumors, as well as determining therapy." (PMID 22510481, 2012). "We analyze the impact of 100 specific miRNA inhibitors (anit-miRNAs) on this pathway and propose that the embedded miRNA-network can help to identify new drug targets of the EGFR signaling pathway and thereby support the development of new therapeutic strategies against cancer." (PMID 22253908, 2012). "Aberrant EGFR expression and signaling are found in various kinds of human cancers." (PMID 22489192, 2012).
cancer (continued). "The study suggests that supplementation of EGFR kinase inhibition with strategies to target cancer stem cell-like populations may increase effectiveness of EGFR inhibition therapies." (PMID 22433462, 2012). "Its expression is downregulated in a variety of human cancer supporting the hypothesis that decreased expression of LRIG1 unleashes EGFR signaling, which might contribute to tumorigenesis." (PMID 22589739, 2012). "Spheroid cultures are regarded as a suitable in vitro model of peritoneal metastasis especially with regard to their anchorage-independent growth, which resembles floating cancer cell aggregates in ascites; however, the EGFR pathways in spheroid cultures are not fully understood." (PMID 23046546, 2012). "However, the cancer eventually progresses during treatment with EGFR inhibitors, even in the patients who respond to these drugs initially." (PMID 22433462, 2012). "In addition to gene mutations, copy number alterations of EGFR, KRAS, PIK3CA and other signaling mediators are also critical factors that drive cancer development and determine prognoses and the sensitivity to anticancer drugs." (PMID 22994622, 2012). "Collectively, the increase in active Src (pSrc Y416), EGFR and AnxA2 upon Herceptin therapy and decrease in phosphorylation of Src and EGFR suggests that the cancer cells reprogram themselves by upregulation of a group of proteins which work together to overcome any stress such as Herceptin therapy." (PMID 22957061, 2012). "Based on our simulation results, we suggest that an anti-mir-21 (p-value: 1.90e-06) could be an effective anti-cancer drug also for other types of cancer with elevated EGFR signaling." (PMID 22253908, 2012). "Based on these observations, we speculated that CSC selection during prolonged exposure to EGFR TKIs may play a role in eventual progression of cancer after a period of successful response." (PMID 22433462, 2012). "Recent studies documented that IGFBP-3, one of EGFR downstream targets, plays an important role in modulation of radiosensitivity of different human cancers, and EGF could down-regulate IGFBP-3 expression in esophageal squamous carcinoma cells." (PMID 23232108, 2012). "Several groups identified that EGFR inhibitors could improve RT response and local control of human tumors, providing a kind of additional agents in anti-cancer therapy." (PMID 23232108, 2012). "We discovered that decorin evoked growth inhibition in vitro, enhanced apoptosis and blocked EGF- and FGF-mediated evasion from Matrigel (not shown), indicating that decorin exerts similar inhibitory activity on EGFR and Met dependent pathways as shown for other carcinoma cells." (PMID 23029096, 2012). "The EGFR overexpression by E2 depletion may be considered within the spectrum of the survival mechanisms to avoid cell death in carcinoma cells." (PMID 23227519, 2012). "Several members of the ADAM family are highly expressed in a variety of human carcinomas, likely contributing to tumor development and/or progression through the release of epidermal growth factor receptor EGFR ligands or effects on cell-cell or cell-matrix adhesion." (PMID 22662180, 2012). "• WT1 Peptide Vaccination in Carcinomas.• Prior treatment with EGFR inhibitor chemotherapy..." (PMID 23282337, 2012). "A blockade of EGFR results in the inhibition of growth in several human carcinoma cell lines." (PMID 22937740, 2012). "Therefore it is reasonable to prescribe a β-blocker to cancer patients; however, as the EGFR is involved in many cancers care should be used when prescribing a drug that activates the EGFR, such as biased agonists." (PMID 21476970, 2011). "This could have effects on the expression of the miRNA target, EGFR, and thus may exert its influence in cancers." (PMID 21326606, 2011).
cancer (continued). "Additional proteins, such as growth factor receptors, are also used as markers of MDR; for example, over-expression of epidermal growth factor receptor (EGFR) is often associated with aggressive phenotypes and is used as a MDR marker in certain types of cancer." (PMID 21320311, 2011). "The hypothesis was based on the notion that skin toxicity may be a surrogate for the inhibition of EGFR TK phosphorylation in the cancer itself." (PMID 21878940, 2011). "Given the link between altered expression of IR isoforms and resistance to the EGFR inhibitor gefitinib, it is clear that aberrant expression levels of IR-A and IR-B may have significant functional effects on cancer progression." (PMID 22046260, 2011). "Thus, in combination of therapeutic strategies that aim to inhibit autophagy in patients treated with conventional chemotherapy or novel targeted therapy with EGFR-TKIs represents a promising approach with higher efficacy for cancer patients." (PMID 21655094, 2011). "It has already been suggested that HIF-1 alpha could be a novel response marker for EGFR inhibitors in cancer cell lines that overexpressed EGFR." (PMID 21966417, 2011). "As the integration process disrupts most of viral genes, sparing only E6 and E7, they suggested that the E5-related increase in EGFR expression could be lost in cancer due to the integration process resulting in abrogation of E5 expression." (PMID 21407808, 2011). "Indeed, treatment of EGFR-positive cancer cells with CL4 strongly inhibits both the EGF-induced tyrosine phosphorylation of EGFR and ErbB2 and the Hrg-dependent tyrosine phosphorylation of EGFR and ErbB3." (PMID 21915281, 2011). "Caspase-6 signalling induced by an EGFR inhibitor might contribute to the induction of apoptosis in SN38-resistant cancer cells." (PMID 21997136, 2011). "On the other hand, different EGFR antagonists may have different effects on cancer-related inflammation, which also needs to be translated into differentiated strategies." (PMID 24212794, 2011). "Combination LON/PTX therapy using EGFR-targeted NPs represents a new approach for the treatment of MDR cancer; this approach addresses the clinical demand for new drug combinations and provides a solution to chemotherapy associated toxicity through the use of a nanocarrier system." (PMID 21931642, 2011). "Thus, inhibition of autophagy has the potential to improve the clinical efficacy of EGFR-TKIs for cancer treatment." (PMID 21655094, 2011). "Hence, a key question in EGFR signalling in cancer is how ADAM protease activity and subsequent shedding of EGFR-ligands is regulated." (PMID 21386996, 2011). "EGFR overexpression is detected in healthy mucosa in cancer patients (field cancerization) that will increase in proportion to observed histological abnormalities such as hyperplasia, carcinoma in situ and invasive carcinoma, indicating that it is an early event in HNSCC." (PMID 21776391, 2011). "In the field of cancer, intrabodies have been used to modulate the expression of proteins upregulated in tumors, such as erbB-2, interleukin-2 receptor, cyclin E (cell cycle protein), and EGFR." (PMID 24212823, 2011). "Endocytosis and receptor degradation induced by anti-EGFR MAbs culminate in the inactivation of growth factor receptors and suppression of downstream signaling pathways, reducing the proliferative/survival potential of cancer cells." (PMID 22185378, 2011). "We then simulate the sustained EGFR activation in EGFR addicted cancer cells." (PMID 22194952, 2011). "Epidermal growth factor receptor (EGFR) is another recognized target for cancer treatment." (PMID 21559248, 2011). "Anti-EGFR immunotherapeutics in cancer treatment is undergoing intensive study." (PMID 22096483, 2011). "Clinical assessment of ERBB2 and EGFR amplification may represent an important factor for the development of personalized treatment programs for gastic cancer." (PMID 21689422, 2011).